CD4 (CD4 molecule)
Diseases named in the same sentence as CD4 in open-access papers (continued):
Sharing a sentence is not in itself a finding about the gene and the disease.
Opportunistic infection (continued). "These include the level of education, marital status, family size, advanced disease stage, presence of opportunistic infections, CD4 count less than 200 cells/mm3, substance use, eating problems, ART drug adherence, and the presence of nutritional counseling." (PMID 37733681, 2023). "Treatment should be deferred in patients at risk for developing immune reconstitution inflammatory syndrome (IRIS), which is possible in treatment naïve patients, presenting with opportunistic infections and a low CD4 count (< 50 cells/μL)." (PMID 38633911, 2023). "This analysis supports retaining baseline CD4 testing to avert deaths from TB and CM, the two most deadly opportunistic infections among patients with AHD." (PMID 36880429, 2023). "Although most of the patients had an available CD4 count tested within a 6-month period (26; 63.4%), many of them did not receive co-trimoxazole prophylactic treatment against opportunistic infections, such as Pneumocystis jirovecii pneumonia." (PMID 38633911, 2023). "We did not collect information on the extent of viral suppression and immunological status (viral load count and CD4 count), opportunistic infections (current and past), and duration of HIV infection and ART use." (PMID 37596620, 2023). "Yet, we observed that there was a remarkable decline in CD4 count testing at the baseline necessary to detect PLHIV who should benefit from a preventive care package against opportunistic infections." (PMID 38020352, 2023). "Living in a rural, lower CD4 count (< = 200 cells/mm3 and 201–350 cells/mm3), poor adherence, and recent opportunistic infection at baseline were found to be predictors of first-line ART virological failure." (PMID 38033131, 2023). "Almost all patients (60.6%) coinfected with opportunistic infections had CD4 + T values below 200 cells/μL." (PMID 36413338, 2023). "Unsurprisingly, two of three patients had CD4+ counts less than 200 cells/μl and these patients also had a history of other opportunistic infections such as Pneumocystis pneumonia, leading to the death of one patient." (PMID 37711607, 2023). "Destruction of existing CD4+ T cells and the inability to activate new CD4+ T cells caused by HIV infection reduced the absolute CD4+ T cell count and increased the risk of opportunistic infection." (PMID 36851658, 2023). "CD4 count monitoring carries weight in the decision-making process of initiating prophylaxis against opportunistic infections." (PMID 38633911, 2023). "Our patients presented an altered viro-immunological status (with a median CD4+ lymphocyte count of 47 cells/mm3), a favorable condition for opportunistic infections, particularly TBM." (PMID 38131680, 2023). "Non-compliance with the treatment causes resistance to the drugs, an increase in HIV viral load, and a decrease in the number of CD4+ cells, preparing the ground for the development of opportunistic infections." (PMID 37887742, 2023). "Early initiation antiretroviral therapy has direct effect on boosting the immunity, suppressing viral replications and increases the CD4 count, so that the occurrence of opportunistic infection will reduce the incidence of OIs." (PMID 37205221, 2023). "From this study, hemoglobin level, weight, and opportunistic infection of other disease were statistically significant at a 5% level of significance for the log CD4 count and TB status of patients jointly." (PMID 38974259, 2023). "Descriptive statistics were computed, and differences in pulmonary function based on CD4+ T-cell counts, viral load, and opportunistic infection were analyzed." (PMID 38022158, 2023). "In total, 34 patients (47.9%) had opportunistic infections (OIs), the median CD4+ T cell count was 73.0 (33.0-149.0) cells/μL." (PMID 38029233, 2023). "Many of the opportunistic infections were identified in stages 2 and 3 (25.75%, and 32.34%), when the CD4 T-lymphocyte level was under 500 cells/μL." (PMID 36984440, 2023).
Opportunistic infection (continued). "This Goldilocks nature of CD4+ T cell help is highlighted by the multiple opportunistic infections, allergies, and autoimmunity that arise in patients following ablation or dysfunction of the CD4+ T cell compartment." (PMID 37892982, 2023). "CD4+T cell counts help predict the course of Cryptosporidium infection, as in many other opportunistic infections." (PMID 36851577, 2023). "Comorbidities, opportunistic infections, side effects, CD4 count and viral load are all indicators of “wellness” and ongoing monitoring of these clinical variables is required to maximise quality of life." (PMID 37605150, 2023). "Variables like CD4 count, opportunistic infection, INH prophylaxis, and severely stunted had the statistically significant result of the log-rank test with (P-Value <0.05)." (PMID 37471340, 2023). "Pathogen detection was high in those with CD4+ cell counts <200 cells/μl, indicating increased opportunistic infections (specifically Cryptosporidium spp)." (PMID 37682831, 2023). "Co-infection of HIV/TB, functional status, age category of children, WHO clinical stage, and opportunistic infections are potential predictors of CD4 cells count change." (PMID 38087261, 2023). "The present CD4 cell count of patients who had opportunistic infections was lower than that of their counterparts." (PMID 38087261, 2023). "It prevents further replication or multiplication of the virus, reduces the patient’s viral load, increases CD4 counts, reduces the likelihood of opportunistic infections and patient hospitalizations, improves patient’s quality of life and reduces mortality." (PMID 37014900, 2023). "Essential consideration should be given to pre-transplant HIV-RNA viral load and CD4 count, presence of opportunistic infections and potential for DDIs with following initiation of HT therapies." (PMID 37568163, 2023). "Although the HRQL of people living with HIV is influenced by the CD4 count and opportunistic infections, it was more influenced by decisional conflict in the present study." (PMID 36859482, 2023). "Management of common complications of opportunistic infections: PCP should be prevented in patients with CD4+ T lymphocyte count <200 cells/μL or a history of oral candidiasis, and a combination of sulfamethoxazole can be used for prevention." (PMID 38126075, 2023). "CD4+ T-cell count recovery is essential for the immune function of PLWHA, which is related to the risk of acquiring opportunistic infections and mortality." (PMID 36294397, 2022). "Baseline characteristics were generally similar between the two study arms with the exception that the proportions of participants with opportunistic infections and CD4 counts < 200 cells/μL were higher in the 2DR arm compared with the 3DR arm." (PMID 34983415, 2022). "Those with CD4+ T-cell counts below 250 cells/mm3 were more likely to manifest opportunistic infections, while medication duration had minimal influence on the prevalence of orofacial opportunistic infections." (PMID 36232165, 2022). "Patients with a lower CD4 cell count were found to be significantly associated with the failure of second-line ART and have a higher probability of developing different opportunistic infections, all of which are more apt to cause death." (PMID 35126600, 2022). "The impairment of cell-mediated immunity (low CD4 cell count and lower CD4/CD8 ratio) has also been suggested as a risk factor for opportunistic infections in patients with sarcoidosis." (PMID 35425769, 2022). "Participants with CD4 counts below 350 cells/mm3 were considered immunocompromised and likely to develop opportunistic infections." (PMID 36483323, 2022). "A CD4+ T cell response towards an occult or a previously known opportunistic infection is the most accepted theory, and it usually occurs in the setting of a rapid rise in the CD4+ T cell count after profound depletion." (PMID 36675837, 2022).
Opportunistic infection (continued). "When CD4+T lymphocyte count < 200 cells/ul, the probability of fatal opportunistic infections increases significantly." (PMID 36419079, 2022). "Studies on adults living with HIV also reported that middle ear pathologies result from opportunistic infections because of a low immune system resulting from a declined number of CD4 T cells." (PMID 36453796, 2022). "In this study, one opportunistic infection, candida Albicans occurred in a patient with CD4+T lymphocyte count < 150 cells/ul." (PMID 36419079, 2022). "This is due to the fact that there is linkage between opportunistic infections and level CD4 cell counts." (PMID 35421084, 2022). "Both deaths involved PLHIV with severe immunosuppression (CD4+ TL < 200 cell/mm3) and opportunistic infection." (PMID 36548687, 2022). "This potentially affected the viral load as well as the CD4 levels of the subjects, hence their altered risks in getting opportunistic infections." (PMID 36355894, 2022). "Opportunistic infections like HIV and Mtb infections have been shown to rely heavily on CD4+ T-cells, which serve as predictors for risk of infections." (PMID 36012562, 2022). "Patients with CD4 lymphocyte counts < 200 mm3 and viral loads ≥ 50 mm3 had higher mortality, although most of the patients received treatment for opportunistic infections." (PMID 36123430, 2022). "Based on the most recent CD4 counts from the chart review, greater than half (56.8%) of the participants had CD4 counts of 500 cells/μl or less; among them, 69.5% had opportunistic infections." (PMID 35558427, 2022). "Further, these are patients with severe immunosuppression making them prone to other opportunistic infections before their CD4 counts improve." (PMID 35246128, 2022). "Presumably, more functioning CD4 cells allows for a more robust immune response against the opportunistic infection." (PMID 36675867, 2022). "The 4-point scoring system covers the four risk factors included in the final multivariate model (ART status = 1, recent absolute CD4 = 1, opportunistic infection = 1, and any comorbidity = 1)." (PMID 36192742, 2022). "Before the advent of ART, invasive aspergillosis in HIV-infected individuals tended to occur when CD4 T-cell counts <100 cells/μl, especially in patients with prior or concomitant opportunistic infections." (PMID 36439143, 2022). "Studies showed low CD4+ T-cell count was strongly associated with disease prognosis, making HIV patients more susceptible to virological failure, opportunistic infections, tumors, and even death." (PMID 36700216, 2022). "Studies of the various trends in the implied underlying causes of neuropathy date back to the beginning of the HIV epidemic, such as the opportunistic infections specific to it and the overall disease progression characterized by the CD4 count." (PMID 35844323, 2022). "Medical appointments, HIV testing and counseling services, opportunistic infection treatment, medicine supply, and routine viral load and CD4 T-cell count tests were interrupted." (PMID 36408047, 2022). "Highly active anti-retroviral therapy (HAART) can reduce viral load and recover the number of CD4+ T cells, which promote immune reconstitution, prevent opportunistic infection, and improve the quality of life in HIV-1-infected patients." (PMID 36411423, 2022). "For CD4+ T-cell counts, three out of four studies identified significantly more orofacial opportunistic infections among children with either less than 250 CD4+ T cells/mm3 or 15% CD4+ T cells." (PMID 36231240, 2022). "PLWHA are vulnerable to various opportunistic infections, especially during the initial phase of cART, when CD4+ T cell count <200/mm3." (PMID 36355915, 2022). "In people with HIV infection, the marked decline in CD4+ cell numbers results in profound immunodeficiency and the development of opportunistic infections, often sequentially." (PMID 35578381, 2022).
Opportunistic infection (continued). "CD4 T-cell lymphopenia was observd in four patients (P1, P2, P4, and P5), although opportunistic infections were rarely observed." (PMID 35145548, 2022). "CD4+ ranges from 18 to 1,335 cells/mm3, and we defined immunosuppression at CD4+ < 200 cells/mm3, which can lead to opportunistic infections." (PMID 35371792, 2022). "An increase in CD4 cell counts reflects rapid immune recovery among HIV-infected patients, associated with higher CSF fungal clearance and better protection against opportunistic infection." (PMID 35473805, 2022). "The available data examining the impact of the occurrence of opportunistic infections on CD4 recovery after antiretroviral therapy introduction are lacking." (PMID 36298842, 2022). "The CD4 cell count at the initiation of ART is the most important predictor of disease progression, and determines opportunistic infection (OI) risk stratification, when to start or stop prophylaxis for OI and guidelines for monitoring response to treatment." (PMID 35192739, 2022). "Idiopathic CD4 T cell lymphocytopenia (ICL) is a rare entity characterized by CD4 T cell count of <300 cells/mm3 along with opportunistic infection for which T cell marker expression remains to be fully explored." (PMID 33450836, 2021). "These opportunistic infections are the result of a severe depletion of CD4+ lymphocytes, which are central mediators of immune response, coordinating both cellular and humoral responses against infections." (PMID 33643320, 2021). "Depression was significantly higher among adults on ART who have widowed marital status, poor medication adherence, low social support, CD4 count ≤ 200, adverse drug reactions, presence of opportunistic infections, and perceived social stigma." (PMID 34721902, 2021). "The progressive immunodeficiency caused by the decrease of CD4+ T lymphocytes during HIV infection is responsible for the installation of AIDS, leading the individual to a predisposition to opportunistic infections and a lower quality of life." (PMID 32623456, 2021). "Patients who had a history of ART switching, major opportunistic infections, a lower baseline CD4 count, an older age, and received nevirapine-based regimens had an increased risk of death." (PMID 34641922, 2021). "From the statistical results of P-value, the prediction value of CD4 for postoperative opportunistic infection was better than that of HIV RNA." (PMID 33436856, 2021). "The clinical characteristics of the patients, including age, sex, CD4+ T cell count, and prevalence of hepatitis or other opportunistic infections, were collected and compared." (PMID 33777838, 2021). "Poor housing conditions, having an opportunistic infection, low CD4 count, starting ART at the advanced HIV stage, don’t take IPT, and being poorly adherent to antiretroviral therapy were associated with the occurrence of TB after initiation of ART." (PMID 33724992, 2021). "During the pandemic, the VA Central Office recommended that newly diagnosed PWH with an opportunistic infection, low CD4 count, or serious ARV adverse event should be seen in an expedited matter in‐person or virtually, depending on patient preference." (PMID 34713585, 2021). "The prevalence of thrombocytopenia and anemia were aggravated by a CD4+ T lymphocyte count of <200 cells/μL, increased viral load and coinfections or opportunistic infections." (PMID 32623456, 2021). "Several cases of Immune Reconstitution Inflammatory Syndrome (IRIS) have been reported in the clinical practice when CD4 T‐cell immunity has been re‐established in a context of immunodeficiency and concurrent opportunistic infections." (PMID 33475257, 2021). "In fact, patients with depilation of CD4 count can develop more severe disease or advanced opportunistic infections including pneumocystis pneumonia, diarrhoea, oral/oesophagal candidiasis which leads to compilation and death." (PMID 34932563, 2021).
Opportunistic infection (continued). "Fourth, we did not assess clinical parameters such as clinical stage, medical history, presence of opportunistic infections, CD4 count and viral load." (PMID 34727943, 2021). "In this study, 483 (93.10%) were at WHO clinical stage I, 123 (23.70%) were diagnosed with opportunistic infection within the last six months, and majority, 282 (54.30%), had moderate CD4 category with a CD4 count of 200-499 cells/mm3." (PMID 33376735, 2020). "Eligible patients were patients with CD4 < 200 cell/μl and presenting with at least 1 of 4 opportunistic infections." (PMID 33028245, 2020). "In fact, CD4 count is essential for identifying late presenters that require urgent care, including immediate opportunistic infections treatment, in order to improve their prognosis." (PMID 32522235, 2020). "This study found that women with symptomatic HIV clinical stage IV for anxiety and clinical stage III for depression, CD4 cell count below 250 cells/mm, and opportunistic infection were more likely to suffer from anxiety and depression." (PMID 32742296, 2020). "The CD4+ is a surrogate marker of immune status and patients with CD4+ <200 cells/mm3 have an increased morbidity and mortality due to opportunistic infections." (PMID 31967541, 2020). "Opportunistic infections (OIs) are the leading cause of morbidity and mortality in this population with advanced HIV disease (defined as CD4+ T-lymphocyte CD4 count <200 cells/μl or World Health Organization (WHO) clinical stage 3 or 4) 5–7." (PMID 34394217, 2020). "In our study, most subjects already received ART for years which presumably led to relatively high median CD4 count and low occurrence of opportunistic infections." (PMID 32448151, 2020). "Many patients have an initially low CD4 count, and it can often be confused for opportunistic infections." (PMID 32399323, 2020). "The rapid increase in CD4 cell count provides better protection against opportunistic infections in the HIV-infected persons." (PMID 32736608, 2020). "Undernutrition was also much higher in patients in WHO clinical stage three and four, CD4 cell count less than 200 cells/mm3 and in patients with a past opportunistic infections." (PMID 32163485, 2020). "This is because a small fraction of those whose timely ART initiation is delayed until after the disruptions will have progressed to the point at which their CD4 count has fallen too low to be reconstituted or opportunistic infections have become unmanaged." (PMID 33089116, 2020). "As individuals with low CD4 count tend to have reduced immunity, higher incidence of opportunistic infection and hospital admission." (PMID 32818041, 2020). "Previous work has suggested a number of HIV-specific factors, including CD4 count, opportunistic infections, and the use of antiretroviral therapy, that affect PA levels in people living with HIV." (PMID 32878040, 2020). "The younger age of the infant, the higher baseline level of hemoglobin, the baseline WHO clinical stage II, and opportunistic infections led to changes in CD4 counts." (PMID 32476985, 2020). "This review found that lower CD4 cell count, being on the WHO clinical stage III/IV, presence of opportunistic infections, and poor HAART adherence were the predominant risk factors of HIV treatment failure." (PMID 31959136, 2020). "Opportunistic infections, treatment of opportunistic infections, deaths, antiretroviral treatments, CD4 and CD8 counts are collected." (PMID 32276647, 2020). "Opportunistic infections tend to be more severe as CD4 count decrease below 200 cells/μL; however, infections do not always occur in low CD4 state." (PMID 32448151, 2020). "In addition, there may be a great degree of heterogeneity among individuals experiencing an interruption of ART, with those having a history of low CD4 counts and opportunistic infections more likely to have a substantially higher mortality risk than those with many years of ART or high CD4 counts." (PMID 33089116, 2020).